STRN3 (striatin 3)
Description:
Calmodulin-binding scaffolding protein which is the center of the striatin-interacting phosphatase and kinase (STRIPAK) complexes. STRIPAK complexes have critical roles in protein (de)phosphorylation and are regulators of multiple signaling pathways including Hippo, MAPK, nuclear receptor and cytoskeleton remodeling. Different types of STRIPAK complexes are involved in a variety of biological processes such as cell growth, differentiation, apoptosis, metabolism and immune regulation (Probable).
Synonyms: SG2NA; PPP2R6B; S/G2NA
Tractability: Antibody: its Gene Ontology location is reachable by antibodies, with high confidence; UniProt places it where antibodies can reach, with medium confidence; the Human Protein Atlas places it where antibodies can reach. PROTAC: ubiquitination databases record sites on it; its protein half-life has been measured.
Gene: Protein-coding gene on chromosome 14 (30,893,799 to 31,026,418, reverse strand). Ensembl gene ENSG00000196792.
Subcellular location: Cytoplasm; Membrane
Subcellular location (Human Protein Atlas): Cytosol; Plasma membrane; Actin filaments; Primary cilium
Gene Ontology:
Molecular function: armadillo repeat domain binding; protein binding; protein kinase binding; protein phosphatase 2A binding; protein-containing complex binding; protein-macromolecule adaptor activity; small GTPase binding; calmodulin binding
Biological process: negative regulation of hippo signaling; negative regulation of intracellular estrogen receptor signaling pathway; regulation of hippo signaling; response to estradiol; negative regulation of DNA-templated transcription
Cellular component: FAR/SIN/STRIPAK complex; Golgi apparatus; nucleoplasm; plasma membrane; dendrite; neuronal cell body; postsynapse; protein-containing complex; cytoplasm; membrane
Genetic constraint (gnomAD): Loss-of-function variants: 25 observed, 83.71 expected, observed/expected ratio (o/e) 0.3, 90% interval 0.22 to 0.42. The upper end of that interval is the gene's LOEUF score, 0.42, which puts it in group 1 of 6, group 1 being the genes least tolerant of losing a copy. Missense variants: 837 observed, 918.81 expected, observed/expected ratio (o/e) 0.91, 90% interval 0.86 to 0.96. Synonymous variants: 316 observed, 334.48 expected, observed/expected ratio (o/e) 0.94, 90% interval 0.86 to 1.04.
Homologues: Orthologues: chimpanzee STRN3 (99% identical), macaque STRN3 (99% identical), pig STRN3 (97% identical), mouse Strn3 (96% identical), rat Strn3 (95% identical), guinea pig STRN3 (95% identical), dog STRN3 (92% identical), rabbit STRN3 (88% identical), tropical clawed frog strn3 (77% identical), zebrafish strn3 (72% identical). Paralogues in human: STRN (63% identical), STRN4 (52% identical).